KIT (KIT proto-oncogene, receptor tyrosine kinase)
Diseases named in the same sentence as KIT in open-access papers (continued):
Sharing a sentence is not in itself a finding about the gene and the disease.
melanoma (continued). "Given the therapeutic implications of NTRK fusions, molecular screening for these alterations is recommended in BRAF, NRAS, and KIT wild-type melanomas." (PMID 40508177, 2025). "The KIT/NRAS/BRAF signaling pathway is the dominant pathway in both melanocytes and melanomas, which is why mutations in these oncogenes occur with such frequency." (PMID 40361349, 2025). "We will then analyze several therapeutic trials and case reports that describe the use of c-KIT inhibitors as well as immune checkpoint inhibitors in melanoma treatment." (PMID 41301010, 2025). "As for KIT mutations, in contrast to GIST, exon 11/13 mutations are common in melanoma, potentially indicating therapeutic sensitivity, whereas exon 9 mutations are rare." (PMID 40361349, 2025). "In preclinical models of KIT K641E-mutant melanoma, a hybrid biomimetic nanovaccine combining tumor and dendritic cell membranes significantly enhanced dendritic cell maturation, T-cell activation, and inhibited tumor growth." (PMID 41301010, 2025). "Ongoing clinical trials are investigating combinations of checkpoint inhibitors and targeted therapies in rare melanoma subtypes, including KIT-mutant disease." (PMID 41301010, 2025). "Further experiments confirmed that Artemisinin inhibits melanoma in vitro and in vivo after radical surgery by the c-KIT/PI3K/AKT signaling pathway." (PMID 39744440, 2025). "KIT mutations and amplifications are identified in approximately 15-20% of ALM and mucosal melanomas and in a subset of LMM." (PMID 40984902, 2025). "Multiple phase II trials were conducted in the early 2000–2010s, enrolling patients whose melanomas harbored activating KIT mutations or amplifications in acral, mucosal, or CSD melanoma." (PMID 41301010, 2025). "In this review, we summarize the current understanding of KIT-mutant melanoma, beginning with its clinico-genetic features and the spectrum of KIT mutations implicated in diseases." (PMID 41301010, 2025). "Imatinib, targeting c-KIT and PDGFR mutations, demonstrates therapeutic benefit primarily in acral and mucosal melanoma subtypes, though with lower response rates than BRAF-directed therapies." (PMID 41302945, 2025). "Melanoma is classically driven by mutations in genes such as BRAF, NRAS, and c-KIT, which promote uncontrolled cell growth and survival." (PMID 40725203, 2025). "Research indicates that mutations in multiple genes are closely associated with melanoma development, including BRAF, NRAS, and KIT." (PMID 41346595, 2025). "In melanoma, early intervention in KIT-mutant acral or mucosal subtypes appears to yield superior outcomes." (PMID 41302945, 2025). "KIT negatively relates to favorable prognosis in patients, and its inhibitors like Imatinib receive a moderate therapeutic effect on melanoma patients 27-29." (PMID 39744440, 2025). "Sorafenib (RAF/KIT/VEGFR/PDGFR inhibitor) suppressed tumor growth in KIT-over-expressing melanoma models, and a complete but transient (five-month) response has been documented in a patient with anal mucosal melanoma harboring the exon 11 p.V560D alteration." (PMID 41301010, 2025). "Improving outcomes in KIT-mutant melanoma will depend on continued efforts to address several therapeutic challenges." (PMID 41301010, 2025). "Significant therapeutic progress has been made in melanoma overall, but KIT-mutant disease remains a distinct, challenging subset, defined by unique clinico-pathologic features and KIT pathway activation." (PMID 41301010, 2025). "Current treatment strategies for metastatic KIT-mutant melanoma often combine KIT inhibition with immune checkpoint blockade, aiming to leverage both targeted and immune-mediated effects." (PMID 41301010, 2025).
melanoma (continued). "Most recently in 2022, a pooled analysis of 130 KIT-altered melanoma patients (AM n = 6) demonstrated an ORR of 25%, PFS of 2.7 months, and OS of 21.8 months in AM patients." (PMID 39858514, 2025). "Its potential role in KIT-mutant melanoma was explored in early preclinical work showing that the L576P substitution in exon 11 conferred greater potency for dasatinib over imatinib." (PMID 41301010, 2025). "Sunitinib is a multikinase inhibitor that targets KIT, VEGFR, PDGFR, among others, and has been evaluated in multiple phase II studies for KIT-altered melanoma." (PMID 41301010, 2025). "The genomic landscape of melanoma features numerous genomic alterations with key driver mutations in genes, such as BRAF (45%), NRAS (17%), and KIT (9%), leading to dysregulated cell growth and survival pathways." (PMID 40004220, 2025). "Off-label uses include chordomas, desmoid tumors, advanced KIT-mutant melanoma, and post–allogeneic transplant relapse in CML." (PMID 41302945, 2025). "KIT-mutant melanoma constitutes a rare but well-defined clinico-genetic subset characterized by distinct histological subtypes, anatomic locations, and patient demographics." (PMID 41301010, 2025). "A phase II study (NCT00700882) found that KIT-positive melanoma had a higher partial response rate (18% or 4/22 tumors) than KIT-negative melanoma (5.9% or 3/51 tumors)." (PMID 40399946, 2025). "While targeted therapies and immunotherapy have transformed care for more common types of melanoma, optimal strategies for KIT-mutant melanoma are less well-defined." (PMID 41301010, 2025). "Even melanoma with rarer genetic alterations, such as NTRK fusions or KIT mutations, can increasingly be treated with specific targeted therapies." (PMID 41081438, 2025). "The genes most frequently associated with melanoma pathogenesis include BRAF, NRAS, neurofibromin 1 (NF1), and KIT." (PMID 39859576, 2025). "Other mutations commonly found in melanoma include NRAS (28% of cases), NF1 (14%), and KIT (15-20% in acral and mucosal melanomas)." (PMID 40861441, 2025). "Then, a series of in vitro experiments indicated that overexpression of c-KIT significantly promoted melanoma proliferation, migration and invasion, while LY294002 reversed the trends." (PMID 39744440, 2025). "Actionable gene alterations in BRAF, NRAS, NF1, and KIT are common in Japanese patients with melanoma." (PMID 39823560, 2025). "Together, these insights provide a practical framework to guide ongoing research and inform more effective, personalized therapeutic strategies for patients with KIT-mutant melanoma." (PMID 41301010, 2025). "As a result, they are frequently prioritized in molecular testing panels, particularly in patients with acral or mucosal melanomas where KIT alterations are more prevalent." (PMID 41301010, 2025). "KIT mutations tend to occur in acral, mucosal, and CSD melanomas in older patients, and are often mutually exclusive of BRAF and NRAS mutations." (PMID 41301010, 2025). "For instance, c-KIT (CD117) expression is vital for classifying MCTs, while markers like Melan-A and S100 are essential for diagnosing melanomas." (PMID 41394861, 2025). "To confirm the critical role of KIT in melanoma, we carried out the survival analysis based on 468 melanoma patients in TCGA database, which identified KIT as a significant biomarker negatively related to prognosis in melanoma patients." (PMID 39744440, 2025). "While dasatinib shows activity in KIT-mutant melanoma, especially in preclinical models and isolated cases, its clinical benefit is constrained by modest efficacy, short duration of response, and a narrow therapeutic window due to toxicity." (PMID 41301010, 2025). "Preclinical studies of ponatinib reported promising results, demonstrating potent antitumor effects in KIT-mutant melanoma models." (PMID 40508177, 2025). "The prospective NICAM phase II trial further evaluated nilotinib in KIT-mutant acral and mucosal melanoma." (PMID 41301010, 2025).
melanoma (continued). "Sunitinib, which inhibits KIT and vascular endothelial growth factor receptors, also demonstrated a limited response in advanced melanoma patients." (PMID 39858514, 2025). "A phase II trial in China evaluating the efficacy of treatment with imatinib in 11 c-KIT-mutant or -amplified mucosal melanoma patients noted a median PFS of 3.5 months and a DCR of 53.5%." (PMID 39001457, 2024). "The variety of KIT alterations including complex mutations across multiple exons with or without gene amplification creates a complicated scenario for successful targeting of KIT protein in melanoma." (PMID 38417447, 2024). "The current landscape of melanoma research, with its exploration of NRAS, TMB, BRAF, EGFR, c-KIT, and other mutations, offers a promising trajectory for future endeavors in understanding and combatting this disease." (PMID 38534309, 2024). "Acral melanomas, having no direct association with sun exposure, although having mutations in BRAF, NRAS, NF1, and KIT, show a lighter and different mutational burden in comparison to low-CSD or high-CSD melanomas." (PMID 38927967, 2024). "Melanoma patients over 65 treated with BRAF/MEK or c-KIT inhibitors were retrospectively identified, and their data were analyzed for treatment efficacy and toxicity." (PMID 39207855, 2024). "Clonal dynamics on therapy were investigated in a patient with KIT mutant mucosal melanoma and a mixed clinical response to the cKit inhibitor imatinib: using WES and subsequent targeted sequencing to track ctDNA mutation profiles over time." (PMID 39293399, 2024). "Ongoing studies are exploring the effectiveness of other KIT inhibitors, such as nilotinib and ripretinib, in treating melanoma." (PMID 39199633, 2024). "Other driver oncogenes seen less frequently in melanoma are NRAS and c-KIT with activating mutations." (PMID 39207855, 2024). "Our data show that nilotinib has activity in the setting of KIT mutant melanoma, comparable to other KIT inhibitors with toxicity profiles consistent with previous reports." (PMID 38417447, 2024). "Five out of the seven melanoma brain metastases harbored the BRAF V600E mutation, and two out of the seven cases had other less frequent mutations (one NRAS mutation, one KIT mutation)." (PMID 39204387, 2024). "Instead, high-CSD melanoma is characterized by a more miscellaneous set of MAPK pathway mutations, such as BRAF V600K, NRAS, or KIT mutations, or inactivation of the negative regulators of Ras, NF1, or RASA2." (PMID 38247727, 2024). "Sunitinib, an oral multi-kinase inhibitor, has been used in melanoma and targets VEGFRs, KIT, and other receptors." (PMID 38791873, 2024). "Similar to other mucosal melanomas, c-KIT, BRAF, and NRAS mutations are frequently detected in female genital melanomas." (PMID 38988710, 2024). "In melanomas, the hyperactivation of the MAPK pathway is mainly through activating mutations in BRAF, NRAS, NF1, and KIT." (PMID 38247727, 2024). "The OFA has been specifically designed to provide comprehensive genomic profiling of solid tumors and includes the mutational study of melanoma-related genes such as BRAF, NRAS, KIT, MAP2K1, or HRAS." (PMID 39000050, 2024). "Oleacein in melanoma cells reduces the mRNA expression of c-KIT, K-RAS, and PIK3R3, which are crucial effectors responsible for heightened mTOR activation." (PMID 39203892, 2024). "Although this oncogene is activated only in a few percent of melanoma cases, for the sake of KIT + melanoma patients, it should be a part of the melanoma panel." (PMID 39340537, 2024). "The melanoma cell line WM3211, derived from the primary lesion (VGP) and wild type for BRAF, PTEN, N-RAS, and CDK4 and with a mutation at position 576 in the c-KIT gene, showed the lowest tendency to activate caspase-3." (PMID 39596342, 2024).
melanoma (continued). "Melanomas on skin intermittently exposed to sun frequently carry somatic BRAF mutations and have a higher nevus count, while melanomas chronically exposed to solar UVR have a low nevus count and NRAS and KIT mutations." (PMID 38927967, 2024). "The genomic profiling of melanoma tumors revealed several recurrent mutations involved in their pathogenesis and evolution, such as BRAF, NRAS, and KIT, contributing to these tumors’ genomic subtyping." (PMID 38396984, 2024). "NGS allows for the comprehensive screening of multiple genes associated with melanoma in a single experiment, enabling the efficient identification of mutations in key genes such as BRAF, NRAS, and c-KIT." (PMID 38474231, 2024). "The search terms “melanoma”, “mutation”, “surgery”, and “metastatic melanoma” and specific gene names (TMB, BRAF, NRAS, EGFR, c-KIT, MITF, etc.)were used in combination with the Boolean operators AND or OR." (PMID 38534309, 2024). "Human melanomas are often driven by well-defined genetic mutations (e.g., BRAF, NRAS, and KIT mutations) that can be targeted by specific therapies." (PMID 39408717, 2024). "c-KIT mutations, while less common than BRAF and NRAS mutations, play a significant role in certain melanoma subtypes, particularly mucosal and acral melanomas." (PMID 38474231, 2024). "successfully created several zebrafish ‘Fin’ melanoma systems that are driven by genes such as CRKL, GAB2 and NF1, analogous to human melanomas that lack BRAF/KIT/NRAS alterations." (PMID 39627834, 2024). "In a study investigating the genomic profile of 122 acral melanomas using DNA sequencing, mutations in BRAF (21.3%), NRAS (27.9%), and KIT (11.5%) were identified." (PMID 36980308, 2023). "Tumors from animals were more invasive and had higher RAS/MAPK pathway activation, while KIT knockdown increased RAS/MAPK pathway activation in a BRAF‐mutant human melanoma cell line." (PMID 37506147, 2023). "One case of a KIT mutant melanoma (CRUKP9359, clonal V650A) also harbored an extreme clonal copy-number amplification at the KIT-encoding locus, with corresponding elevated KIT expression." (PMID 36977461, 2023). "Acral melanomas harbor KIT, NRAS, and BRAF mutations, mucosal melanomas KIT and NRAS mutations, and uveal and melanomas arising in blue nevi uniquely have GNA11 and GNAQ mutations." (PMID 37841001, 2023). "Among them, genes KIT functions in the regulation processes of cell proliferation, migration, stem cell maintenance, differentiation and the occurrence of melanoma and some other cancers." (PMID 37644423, 2023). "A variety of clinical trials have been conducted to explore the therapeutic value of c‐KIT inhibitors in KIT‐mutant melanomas." (PMID 37403699, 2023). "It was found that expression of the receptor tyrosine kinase c-KIT decreased with melanoma progression, and that miR-221/222 expression increased with tumor progression and was inversely correlated with c-KIT expression." (PMID 36982460, 2023). "In this study, as an extension to our previous work on head and neck mucosal melanomas, we aimed to investigate the BRAF, NRAS, KIT, TERT and GNAQ/GNA11 mutation status of 15 AMs, as well as their clinicopathologic features." (PMID 35642348, 2023). "The receptor tyrosine kinase KIT plays a crucial physiological role in the proliferation and survival of melanoma cells, through the PI3K and the MAPK signaling cascades." (PMID 37958863, 2023). "Some of the most commonly occurring somatic alterations in melanoma include mutations in the BRAF, NRAS, and KIT genes." (PMID 37504268, 2023). "KIT is a proto-oncogene that encodes a receptor tyrosine kinase (RTK) and is considered a driver mutation in melanoma." (PMID 37762707, 2023). "KITLG/KIT signaling also has known roles in human melanoma as well as murine and zebrafish melanoma models." (PMID 37021774, 2023).
melanoma (continued). "Although several case reports have indicated the efficacy of combined KIT inhibitors with immunotherapy in KIT mutant advanced melanoma, related RCTs are urgently required." (PMID 37403699, 2023). "Other somatic mutations have also since been identified in melanomas including TERT, NRAS, NF1, and KIT in approximately 70-85%, 20-30%, 10-15, and 10% of melanomas, respectively." (PMID 37841001, 2023). "Melanoma frequently harbors BRAF, NRAS, or KIT mutations which influence both tumor development and treatment strategies." (PMID 37403699, 2023). "In a large cohort of mucosal melanomas, 3% of AMs showed BRAF, 10% showed NRAS, and 19% showed KIT mutations." (PMID 35642348, 2023). "In melanoma, mutations in BRAF (50%−70%), NRAS (15%−30%), NF1, KRAS and HRAS (in 2 and 1% of patients, respectively), and KIT are responsible for MAPK dysregulation." (PMID 36844227, 2023). "Meanwhile, melanomas arising in high CSD skin, which present as lentigo maligna melanomas, contain more NRAS and KIT mutations." (PMID 37841001, 2023). "In this real‐world study, melanoma patients with BRAF, KIT, or NRAS mutations treated with anti‐PD‐1 adjuvant monotherapy had no statistical difference of DFS compared to patients received IFN or observation." (PMID 37403699, 2023). "LMM is included in high-CSD melanoma and is typically associated with mutations of BRAFV600K, NRAS, NF-1, or KIT." (PMID 35954498, 2022). "An MYSM1 protein quantification showed an incremental increase during the progressive transformation of normal melanocytes into malignant melanoma cells with a correlation with c-KIT expression in melanoma." (PMID 35884430, 2022). "Further studies are required, as the long-term efficacy of c-KIT inhibitors in melanoma patients is uncertain, as well as its efficacy compared to other immunotherapies." (PMID 36232957, 2022). "KIT-mutant melanomas exhibit clinical responses to inhibitors of type III transmembrane receptor tyrosine kinases." (PMID 35893303, 2022). "In contrast, melanomas with WT BRAF, NRAS and NF1 that are driven by activating KIT mutations can be treated with the RTK inhibitor imatinib, yielding response rates of 16–30%; however, most of these responses were partial and transient." (PMID 35234863, 2022). "Results:c-KIT c.1926delA p.K642S*FS mutation in primary and recurrent GIST patients and c-KIT c.1936T>G p.Y646D point mutation in melanoma patients in exon 13 were first demonstrated to be novel targets resistant to imatinib agent." (PMID 35720122, 2022). "Several clinical trials are studying the efficacy of c-KIT inhibitors together with other TKIs or immunotherapies as c-KIT mutant melanoma patients often develop resistance to TKIs." (PMID 35954441, 2022). "Several phase II trials evaluating KIT inhibitors in KIT mutant melanomas have been conducted with modest activity." (PMID 35640549, 2022). "The KIT mutations are most predominant in CSD (8–20%), mucosal (16–25%), and acral (12–23%) melanomas." (PMID 36551688, 2022). "The pathogenesis of malignant melanomas is very complex, including a series of complicated interactions among external events and endogenous triggers, genetic mutations of BRAF, NRAS, and KIT, as well as endogenous and immune-related factors of the tumor." (PMID 35220953, 2022). "Overall, the combination therapy of a KIT inhibitor and immunotherapy offers promise in the treatment of melanoma with KIT alterations." (PMID 35954441, 2022).